RN7SL552P (RNA, 7SL, cytoplasmic 552, pseudogene)
Gene: Miscellaneous RNA gene on chromosome 4 (84,687,725 to 84,688,000, reverse strand). Ensembl gene ENSG00000239466.
Homologues: Orthologues: chimpanzee Metazoa_SRP (99% identical), macaque Metazoa_SRP (90% identical). Paralogues in human: RN7SL1 (82% identical), RN7SL2 (82% identical), RN7SL448P (81% identical), RN7SL3 (80% identical), RN7SL408P (80% identical), RN7SL91P (80% identical), RN7SL709P (80% identical), RN7SL567P (79% identical), RN7SL482P (79% identical), RN7SL630P (79% identical), RN7SL126P (79% identical), RN7SL18P (79% identical), and 707 more.